E2F4 (E2F transcription factor 4)
Description:
Transcription activator that binds DNA cooperatively with DP proteins through the E2 recognition site, 5'-TTTC[CG]CGC-3' found in the promoter region of a number of genes whose products are involved in cell cycle regulation or in DNA replication. The DRTF1/E2F complex functions in the control of cell-cycle progression from G1 to S phase. E2F4 binds with high affinity to RBL1 and RBL2. In some instances can also bind RB1. Specifically required for multiciliate cell differentiation: together with MCIDAS and E2F5, binds and activate genes required for centriole biogenesis.
Synonyms: E2F-4
Tractability: PROTAC: ubiquitination databases record sites on it; its protein half-life has been measured. Other modalities: a drug acting on it is in phase 2 or 3 trials.
Gene: Protein-coding gene on chromosome 16 (67,192,155 to 67,198,918, forward strand). Ensembl gene ENSG00000205250.
Subcellular location: Nucleus
Subcellular location (Human Protein Atlas): Nucleoplasm
Pathways (Reactome):
Cell Cycle: Cyclin A:Cdk2-associated events at S phase entry; Cyclin D associated events in G1; Cyclin E associated events during G1/S transition; G0 and Early G1; G1/S-Specific Transcription; Transcription of E2F targets under negative control by DREAM complex; Transcription of E2F targets under negative control by p107 (RBL1) and p130 (RBL2) in complex with HDAC1
Signal Transduction: SMAD2/SMAD3:SMAD4 heterotrimer regulates transcription
Gene Ontology:
Molecular function: DNA binding; DNA-binding transcription activator activity, RNA polymerase II-specific; DNA-binding transcription factor activity; promoter-specific chromatin binding; protein binding; protein domain specific binding; RNA polymerase II cis-regulatory region sequence-specific DNA binding; sequence-specific double-stranded DNA binding; DNA-binding transcription factor activity, RNA polymerase II-specific; chromatin binding; protein dimerization activity
Biological process: positive regulation of transcription by RNA polymerase II; regulation of DNA-templated transcription; centriole assembly; motile cilium assembly; multi-ciliated epithelial cell differentiation; negative regulation of DNA-templated transcription; regulation of transcription by RNA polymerase II
Cellular component: chromatin; cytoplasm; nucleoplasm; RNA polymerase II transcription regulator complex; DRM complex; nucleus; transcription regulator complex
Genetic constraint (gnomAD): Loss-of-function variants: 16 observed, 39.53 expected, observed/expected ratio (o/e) 0.4, 90% interval 0.27 to 0.62. The synonymous counts are far from expectation, so gnomAD's model fits this gene poorly and the ratio says little. Missense variants: 473 observed, 487.5 expected, observed/expected ratio (o/e) 0.97, 90% interval 0.9 to 1.05. Synonymous variants: 242 observed, 197 expected, observed/expected ratio (o/e) 1.23, 90% interval 1.11 to 1.37.
Homologues: Orthologues: macaque E2F4 (99% identical), chimpanzee E2F4 (98% identical), pig E2F4 (94% identical), guinea pig E2F4 (94% identical), dog E2F4 (93% identical), rat E2f4 (93% identical), mouse E2f4 (92% identical), tropical clawed frog e2f4 (65% identical), zebrafish e2f4 (64% identical). Paralogues in human: E2F5 (51% identical), E2F2 (30% identical), E2F3 (28% identical), E2F1 (27% identical), E2F7 (23% identical), E2F8 (23% identical), E2F6 (19% identical).
Diseases named in the same sentence as E2F4 in open-access papers:
E2F4 is named in the same sentence as 99 diseases in open-access papers, as found by Europe PMC text mining. Sharing a sentence is not in itself a finding about the gene and the disease. The quoted sentences say what the papers report.
breast carcinoma (31 papers, 2010 to 2025). "Increased expression of the E2F4 transcription factor is associated with cancer severity and poorer prognosis in breast cancer." (PMID 35044822, 2022). "In our study, we identified two different alternatively-activated TGF-β signaling pathways, and the E2F5-related sub-pathway is related to breast cancer, while the E2F4 related one is a risk for metastasis and potential worse survival." (PMID 31557971, 2019). "To address this, we examined the association between E2F4 activity and neoadjuvant therapy response across different subgroupings of breast cancer, including ER status, tumor stage, and molecular subtype." (PMID 28464832, 2017). "Examining E2F4 activity scores within stratified groups, such as Oncotype DX risk strata, breast cancer intrinsic subtypes, and pharmacological treatment status, shows that E2F4 activity scores convey additional prognostic information within these strata." (PMID 25440089, 2014). "PARP-1 can also recruit protein MRE11, ATM (ataxiatel angiectasia mutated) to suppress the transcription factors E2F4 and P130 complexes and impact the expression of breast cancer susceptibility genes BRCA1 and RAD5, which transiently protects the DNA gaps and inhibits recombinant." (PMID 36590386, 2022). "The increased E2F4 in breast cancer is also associated with breast cancer liver metastasis." (PMID 33613768, 2021). "Except for known disease proteins of breast cancer that found in the 6 protein complexes, many disease proteins that were associated with many other types of diseases could be found, with examples including E2F4, E2F5, HRAS, JUN, FOS." (PMID 24565064, 2014). "The modest positive correlation of E2F4 expression with WNT ligand expression in bulk BRCA tumour prompted to study the self-renewal of breast cancer CSC by tumour sphere assays." (PMID 38678032, 2024). "E2F4 was highly expressed in hepatocellular carcinoma as well as breast cancers and strongly correlates with poor prognosis." (PMID 36567912, 2022). "The analysis also uncovered a novel regulatory mechanism by which the oncogenic E2F4 transcription factor is up-regulated in breast tumors, linking an intron retention event in E2F4 with unfavorable prognosis in patients with breast cancer." (PMID 35044822, 2022). "We next examined two other gene signatures for clinical outcome prediction in breast cancer, the MammaPrint and the E2F4 signatures." (PMID 35140308, 2022). "Most studies have shown that E2F4 expression is higher in gastric and breast cancer tissues than in pericancerous mucosa tissues, and is significantly associated with survival, which indicates a poor prognosis." (PMID 35840663, 2022). "E2F5 was significantly active in primary breast cancer, and E2F4 was significantly active in the metastasis." (PMID 31557971, 2019). "In the calcium signaling and TGF beta signaling pathways, node E2F5 and E2F4 were significantly active in primary breast cancer and metastasis, respectively." (PMID 31557971, 2019). "Patients with breast cancer exhibiting increased expression of E2F4 target genes displayed a more severe cancer and shorter survival." (PMID 30487158, 2018). "In this study, we applied our signature to predict neoadjuvant therapy response and found that patients with high E2F4 iRASs were more likely to experience pCR than those with low and intermediate scores even when stratifying by breast cancer subtype." (PMID 28464832, 2017). "We applied our previously developed E2F4 genomic signature to predict neoadjuvant chemotherapy response in breast cancer." (PMID 28464832, 2017). "E2F4 individual regulatory activity scores were calculated for 1129 patient samples across 5 independent breast cancer neoadjuvant chemotherapy datasets." (PMID 28464832, 2017). "In this study, we extend this work to assess the performance of our E2F4 signature in multiple independent datasets made up of diverse subtypes of breast cancer that undergo various regimens of neoadjuvant chemotherapy." (PMID 28464832, 2017).
breast carcinoma (continued). "Using this method, we have successfully defined an E2F4 target gene-based signature for predicting survival times of patients with breast cancer." (PMID 25881247, 2015). "We have shown that BASE can accurately infer E2F4 activity in cancer samples based on the target gene set, which stratifies breast cancer patients into good and poor prognosis groups." (PMID 25881247, 2015). "For each breast cancer sample, an E2F4 iRAS was generated using REACTIN based on the sorted relative expression levels of the E2F4 target genes in the sample." (PMID 25440089, 2014). "We evaluated confounding of our results by patient ER and PR status, based on literature linking E2F4 with progression of estrogen-dependent breast cancer cell lines." (PMID 25440089, 2014). "We focus on the E2F4 signature, because we have previously identified it as being prognostic in breast cancer in a large-scale computational screening analysis." (PMID 25440089, 2014). "Using eight independent breast cancer datasets containing over 1,900 unique samples, we stratified patients into low and high E2F4 RAS groups." (PMID 25440089, 2014). "E2F4 activity level also correlates with classification assignment of breast cancers into their intrinsic subtypes." (PMID 25440089, 2014). "The predictive power of E2F4 iRASs for breast cancer survival and the correlation of this signature with cell cycle phase encouraged us to test the effectiveness of the E2F4 signature for patient survival prediction in other cancers." (PMID 25440089, 2014). "Using E2F4 with our REACTIN method and clinical outcome data, we examine E2F4’s regulatory activity in detail as a predictor of survival outcome for breast cancer." (PMID 25440089, 2014). "We have previously shown that E2F4 activity inferred from expression of all genes predicts patient survival prognosis of breast cancer patients." (PMID 25440089, 2014). "E2F4 activity level robustly predicts breast cancer patient survival across a variety of clinical contexts." (PMID 25440089, 2014). "Based on the signature, E2F4 activity is inferred in breast cancer samples and used for predicting clinical outcomes." (PMID 25440089, 2014). "This also restricts the ability to examine the E2F4 signature in certain breast cancer subtypes accounting for only a small fraction of samples." (PMID 25440089, 2014). "These are preliminary results, and more investigations are needed to more precisely understand the role of the E2F4 regulatory program in tumorigenesis and progression of cancer types beyond breast cancer." (PMID 25440089, 2014). "We evaluated our method using E2F4, a well-known cell cycle regulator with an unclear role in cancer progression, and tested its predictive power for patient survival in breast cancer." (PMID 25440089, 2014). "More detailed analyses - in datasets with larger number of samples and with controlling for other factors - should be carried out before we can conclude the significance of the E2F4 signature in non-breast cancer types." (PMID 25440089, 2014). "Genes in our E2F4 signature were 21-fold more likely to be correlated with breast cancer patient survival time compared to randomly selected genes." (PMID 25440089, 2014). "Using this method of generating E2F4 iRASs for given samples, we turned to breast cancer based on our prior work to examine E2F4’s inferred functional activity through iRASs and its ability to predict survival prognosis." (PMID 25440089, 2014). "Interestingly, cell cycle-associated proteins, such as the cyclin-dependent kinases (CDKs) and the E2F4 oncogenes appeared to be strongly dysregulated between subgroups, displaying an increased activity in the most severe breast cancer subtype, Basal-l." (PMID 41073799, 2025). "Interestingly, a prior study in HER2- has identified a different E2F Transcription Factor (E2F4) as having a role in treatment resistance in ER+ breast cancer and also in the original analysis of our same ER+ cohort." (PMID 39057065, 2024).
breast carcinoma (continued). "We validate our framework with three widely used clinical biomarkers (Oncotype DX, MammaPrint and E2F4) for breast cancer, which we successfully discover those biomarkers have higher accuracy of predictability within a subset of patient with specific clinical or genetic features." (PMID 35140308, 2022). "Similar to our results, Khaleel and colleagues reported that E2F4 could serve as an outcome prognosis predictor for breast cancer." (PMID 33613768, 2021). "E2F4 regulatory activity level predicts breast cancer survival outcome and may be of use in augmenting prognosis in cancer types." (PMID 25440089, 2014). "Furthermore, the fractions of samples with positive E2F4 RAS vary in different intrinsic breast cancer subtypes, consistent with the different survival profiles of these subtypes." (PMID 25440089, 2014). "Survival is favored for patients with negative E2F4 activity scores, suggesting that the upregulation of E2F4 activity is associated with worse breast cancer prognosis." (PMID 25440089, 2014). "Extending beyond breast cancer, we preliminarily analyze E2F4 regulatory activity levels in bladder, colon, non-small cell lung, glioblastoma, acute myeloid leukemia, and Burkitt’s lymphoma cancer types, respectively, and find that they appear prognostic in colon, glioblastoma, and bladder cancer." (PMID 25440089, 2014). "ER + breast cancer patient RNAseq data from TCGA revealed an association of ROS and PPAR signaling with NNAT expression and in silico analysis of the NNAT promotor revealed consensus binding sites for NRF1 and PPARα/PPARγ, as well as the cell cycle transcription factor, E2F4." (PMID 37400769, 2023). "Thus, this retained intron event might represent a regulatory mechanism by which splicing leads to up-regulation of the E2F4 oncogene in breast cancer." (PMID 35044822, 2022). "Briefly, the ER + breast cancer cell lines, T47D and ZR75, were co-transfected with the NNAT promoter-reporter construct, and plasmids that constitutively expressed E2F1, E2F4, NRF1, PPARα/RXR, PPARγ/RXR, or control (pLX304)." (PMID 37400769, 2023). "Further, the genes were also enriched for targets of several transcription factors, like NELFE, E2F4 and CREB1 which are known to play key roles in several cancers, including breast cancer." (PMID 36584096, 2022). "E2F1 and E2F4 induce whereas pRb/RBL2 reduce WNT ligand expression (e.g. WNT7A, WNT7B, WNT10A, WNT4) thereby regulating self-renewal, chemoresistance and invasiveness of CSCs in both PDAC and breast cancer, and fibroblast proliferation." (PMID 38678032, 2024). "E2F4, FOXM1, and E2F1 are all indicated in development and progression of breast cancer." (PMID 38886591, 2024). "Collectively, the observations that NNAT is transcriptionally regulated by E2F4 and that overexpression of NNAT decreased ER + breast cancer cell proliferation suggest that cell cycle inhibition in response to ROS or PPAR signaling is potentially sensed and reinforced by NNAT." (PMID 37400769, 2023). "Conversely, overexpression of either E2F4 or E2F6, as well as E2F5 which also forms a DREAM complex, was able to repress A3B expression to varying extents in multiple different breast cancer cell lines." (PMID 32985974, 2020). "We defined a prognostic signature, the E2F4 regulatory activity score, and showed it to be significantly predictive of patient outcome in breast cancer regardless of treatment status and the states of many other clinicopathological variables." (PMID 25440089, 2014). "Out of the 260 breast cancer samples of the Vijv dataset, 151 have a positive E2F4 activity score and 101 have a negative E2F4 activity score." (PMID 23885756, 2013).
ovarian carcinoma (14 papers, 2010 to 2026). A malignant neoplasm originating from the surface ovarian epithelium. "To date, the role of E2F4as is unclear with E2F4, and cell cycle and apoptosis studies have been conducted to clarify the role of E2F4as in ovarian cancer cell lines." (PMID 33287341, 2020). "Taken together these results suggest that E2F4 is an activator of BRCA1 transcription in ovarian cancer cells." (PMID 31604914, 2019). "The mRNA levels of E2F4 in ovarian carcinoma (fold change = 1.573 and p–value = 7.77E-04) and ovarian serous carcinoma (fold change = 2.574 and p–value = 1.01E-06) were significantly higher than those in the normal samples in Bonome's and Welsh's datasets." (PMID 30967995, 2019). "Our mechanistic studies discovered that ZC3H18 and E2F4 depletion reduces BRCA1 levels in ovarian cancer cell lines and low-passage, short-term ex vivo-cultured HGSOC PDX models freshly isolated from mice." (PMID 31604914, 2019). "It was found that interferon-gamma treatment for ovarian cancer caused a reduction of the proliferation-promoting TFs E2F1 and E2F2, at the same time it also increased the inhibiting TFs E2F4 and E2F5." (PMID 20181230, 2010). "The lncRNA GAS5 may regulate the expression of PARP1 by recruiting the transcription factor E2F4 to its promoter, affecting the activity of the MAPK signalling pathway, promoting apoptosis and causing G0/G1 arrest in ovarian cancer cells." (PMID 35725373, 2022). "This study showed that E2F4as expression may contribute to the development of ovarian cancer by reducing E2F4 expression, reducing the level of cell cycle inhibitors, and mediating the proliferation of ovarian cancer cells." (PMID 33287341, 2020). "Taken together, we hypothesize that E2F4 could have the same oncogenic effects as E2F1 on ovarian carcinoma by suppressing miR-519d." (PMID 28146423, 2017). "Similarly, a high E2F2 to E2F4 ratio was reported to be of prognostic value for ovarian cancer-free survival." (PMID 21694727, 2011). "The elevation in cyclin D levels in ovarian cancer cells with low levels of G1 CDK inhibitors unbalances G1 cell cycle regulation and enables a premature exit from the quiescent state, with a loss of sequestered E2F4 from p130/Rb2, with subsequent apoptosis and cell death." (PMID 25061503, 2014). "In epithelial ovarian cancer, GAS5 interacts with E2F4 (E2F Transcription Factor 4), recruiting E2F4 to the PARP1 promoter." (PMID 34202777, 2021). "In the combined analysis of CLIP-seq, RIP-seq and RNA-seq data, we identified multiple potential direct binding targets (BCL2L12, RBCK1, E2F4, and CDK16) that may involve in BUD31-mediated ovarian cancer cell survival and proliferation." (PMID 36271053, 2022). "There are some limitations of our study, first of all, whether rapamycin can affect the apoptosis of ovarian cancer cells by targeting GAS5 expression and how to participate in GAS5 target gene (E2F4 or PARP1) regulation need to be further studied." (PMID 31391118, 2019). "In the E2F family of transcription factors, E2F2, E2F3, E2F4, and E2F8 expression is increased and may play oncogenic roles in ovarian carcinoma, and exert the same effects as E2F1." (PMID 28146423, 2017).